BRAF (B-Raf proto-oncogene, serine/threonine kinase)
Diseases named in the same sentence as BRAF in open-access papers (continued):
Sharing a sentence is not in itself a finding about the gene and the disease.
melanoma (continued). "For example, the amplification of BRAF has been observed in dabrafenib and trametinib combination therapy-resistant melanoma and colon cancer patients, with additional variations in BRAF splicing found in the melanoma patients." (PMID 38539548, 2024). "In BRAFV600E+ melanoma cells, an aberrant activation of this intracellular pathway has been reported to mediate resistance to BRAF and MEK inhibitors and to support the acquisition of stem-like properties." (PMID 39199632, 2024). "Forkhead box D3 (FoXD3) is a stem cell/pluripotency transcription factor that can be triggered upon BRAF/MEK pathway inhibition in mutant BRAF melanomas." (PMID 38835349, 2024). "For example, when BRAF and MEK inhibitors are used together in BRAF-mutant melanoma or when EGFR and HER2 inhibitors are combined in HER2-positive breast cancer, there are better treatment responses and a slower development of resistance." (PMID 39001539, 2024). "Over the past several decades, advancements in the treatment of BRAF-mutant melanoma have led to the development of BRAF inhibitors, BRAF/MEK inhibitor combinations, anti-PD-1 therapy, and anti-CTLA4 therapy." (PMID 39336897, 2024). "The effect was even stronger when combined with melanoma standard-of-care BRAF/MEK inhibitors dabrafenib and trametinib, respectively." (PMID 39165562, 2024). "There are three BRAF/MEK inhibitor combinations used for treatment of BRAF V600 E positive melanomas-1) vemurafenib/cobimetinib 2) dabrafenib/trametinib and 3) encorafenib/binimetinib." (PMID 39634188, 2024). "Calcein-AM/PI stainings confirmed the cytotoxic effects previously observed in 2D and 3D BRAF WT melanoma models." (PMID 38263136, 2024). "BRAF V600 substitutions are a predominant type of somatic BRAF alterations in the majority of tumor types (melanoma, colorectal cancer, etc.), however, they account for less than a half of BRAF lesions in lung malignancies." (PMID 38966170, 2024). "Despite the infrequency of BRAF mutations in this melanoma type, genotyping for both NRAS and BRAF is recommended as a result of the effectiveness of available inhibitors." (PMID 39202970, 2024). "In 2015, the Cancer Genome Atlas Program (TCGA) Network suggested a new genomic classification for melanoma: mutant BRAF (31%), mutant RAS (18%), mutant NF1 (21%), and triple WT (26%)." (PMID 39126091, 2024). "The current landscape of melanoma research, with its exploration of NRAS, TMB, BRAF, EGFR, c-KIT, and other mutations, offers a promising trajectory for future endeavors in understanding and combatting this disease." (PMID 38534309, 2024). "Such a mechanism immediately offers an explanation of the inevitable relapse after BRAFi treatment in BRAF-mutant melanoma and points to actionable strategies to overcome it." (PMID 39001489, 2024). "Here, BRAFi/MEKi (BRAF inhibitor/MEK inhibitor)-resistant melanoma cell lines were extensively characterized." (PMID 39175042, 2024). "Compared with a decade ago, the 5-year survival rate for patients with advanced melanoma treated with BRAF inhibitors, MEK inhibitors, or single PD-1 antibodies has improved from 5% to approximately 30%." (PMID 38462618, 2024). "Compared to over 90% of BRAF, RAS, and NF1 subtypes, only 30% of triple WT melanomas are caused by UV." (PMID 39126091, 2024). "The treatment of BRAF-mutant melanoma with BRAF inhibitors is severely limited in clinical practice, in part due to the emergence of drug tolerance via non-genetic adaptation to therapies." (PMID 39001489, 2024). "Instead, high-CSD melanoma is characterized by a more miscellaneous set of MAPK pathway mutations, such as BRAF V600K, NRAS, or KIT mutations, or inactivation of the negative regulators of Ras, NF1, or RASA2." (PMID 38247727, 2024). "In one study, a biosensor that measured CDK2 activity was used to track individual BRAF-mutant melanoma cells as they developed into drug-tolerant cells in response to the BRAF inhibitor dabrafenib." (PMID 38473364, 2024).
melanoma (continued). "In contrast, treatment with PLX4032 didn’t significantly change the expression patterns of HDAC10 and SPARC in BRAF WT melanoma cells (SK-MEL-2 and WM3918)." (PMID 38650694, 2024). "Nonetheless, in some cases metformin accelerates tumor growth in vivo in resistant BRAF-mutant melanoma cells." (PMID 38339003, 2024). "Depletion of HDAC10 and the subsequent upregulation of SPARC activate AMPK signaling and induce autophagy, ultimately suppressing melanoma cell growth and attenuating resistance to BRAF inhibitors." (PMID 38650694, 2024). "While pioneered in melanoma, it is now approved by the Food and Drug Administration (FDA) for all solid metastatic tumors harboring BRAF V600E-mutation where standard therapy has failed." (PMID 38716076, 2024). "For example, some have BRAF mutations, which are often the classic V600E gain-of-function (GOF) mutation that is seen frequently in melanoma and other cancer types, and this is often mutually exclusive with KIT/PDGFRA mutations." (PMID 38730662, 2024). "Inhibiting the BRAF-MEK pathway in melanoma promotes a shift from lactate-producing glycolysis to OXPHOS for ATP production." (PMID 39501277, 2024). "Authors mainly administered a combined drug regimen as it demonstrated superior oncological outcomes, compared to BRAFi monotherapy, in BRAF V600E-mutant melanoma." (PMID 39456573, 2024). "Based on these findings, researchers are against combining BRAF-targeted therapy with immunotherapy in the neoadjuvant treatment of melanoma until further follow-up data can confirm these observations." (PMID 39582535, 2024). "Acral melanomas, having no direct association with sun exposure, although having mutations in BRAF, NRAS, NF1, and KIT, show a lighter and different mutational burden in comparison to low-CSD or high-CSD melanomas." (PMID 38927967, 2024). "Further works should assess the contribution of our newly identified mechanisms involving polyamine biosynthesis and EIF5A hypusination in the context of dynamic rewiring and adaptation of BRAF mutant melanoma upon BRAFi/MAPKi treatment." (PMID 38965534, 2024). "In 2021, the International Neoadjuvant Melanoma Consortium reported the first pooled analysis from six clinical trials of anti-PD-1-based immunotherapy or BRAF/MEK-targeted therapy involving a total of 192 melanoma patients." (PMID 39727691, 2024). "Altogether these data demonstrated that miR-579-3p is positively regulated by MITF transcription factor in BRAF-mutant melanoma cells." (PMID 38472212, 2024). "Challenges and opportunities in potential approaches to personalized immunotherapy for BRAF-mutant melanoma." (PMID 39336897, 2024). "The phase 3 COMBI-AD trial involved patients with stage III BRAF V600 mutant melanoma—according to AJJC 7th edition and stage IIIA with a minimum lymph node involvement of 1 mm." (PMID 38748192, 2024). "Such heterogeneity was reported before, but the main focus was on the MAPK pathway and melanoma-related oncogenic pathways and tumor suppressors, such as PI3K, PTEN, AKT, and CDKN2A, or amplification of BRAF and mutations of the RAS family." (PMID 39001376, 2024). "In CheckMate 066, a randomized phase III trial, nivolumab was compared with dacarbazine (DTIC) in treatment‐naïve patients with BRAF wild‐type advanced melanoma." (PMID 38358050, 2024). "Mutations in the B-Raf proto-oncogene (BRAF) and neuroblastoma RAS viral oncogene homolog (NRAS), common in other melanomas, are less frequent in this variant." (PMID 39202970, 2024). "Given the results observed in the C-14401 trial, lifileucel was evaluated in melanoma patients with unresectable/metastatic disease, untreated with ICIs and treated with BRAF/MEK inhibitors if BRAF-mutated, in the context of the IOV-COM-202 clinical study." (PMID 39727691, 2024). "Combined BRAF and MEK inhibitors therapy has emerged as an optimal treatment of metastatic BRAF-mutated melanoma, with improved survival rates compared with BRAF inhibitors alone." (PMID 39776585, 2024).
melanoma (continued). "Alterations in G2M Checkpoint and E2F targets (which include genes critical for cell cycle progression) were also enriched in BRAF Class 3 melanoma, indicating dysregulation of the cell cycle in these tumors." (PMID 38275886, 2024). "The conversion of BRAF V600E positive nevi to full-blown melanomas is achieved through a plethora of genetic and epigenetic alterations." (PMID 38396984, 2024). "Patients previously treated with the anti-PD-1 and anti-CTLA-4 combination and those with BRAF wild-type melanoma seemed to benefit more from this second-line strategy." (PMID 38956747, 2024). "The high response rate and rapid responses sparked interest in neoadjuvant BRAF/MEK inhibition in resectable melanoma." (PMID 38500654, 2024). "Adjuvant treatment with immune checkpoint inhibitors, such as PD1-antibodies (ICI) ± CTLA4-antibodies (cICI) or targeted therapy with BRAF/MEK inhibitors (TT), has shown a significant improvement in disease-free survival (DFS) for high-risk melanoma patients." (PMID 38743104, 2024). "Another randomized controlled trial was carried out between 2012-2014 on patients with advanced melanoma who progressed after ipilimumab therapy or a combination of ipilimumab and a BRAF inhibitor if they were found to be positive for a V600E mutation." (PMID 38410760, 2024). "In another trial, continuous dosing of combination cobimetinib and vemurafenib (a Type 1 BRAF inhibitor) was compared with intermittent dosing in patients with advanced BRAF-mutant melanoma." (PMID 39759151, 2024). "Targeted therapies developed for melanoma include MAPK inhibitors, BRAFi and MEKi, These target the pathogenic constitutively activated MAPK pathway in BRAF- and NRAS- mutant melanoma cells." (PMID 38533720, 2024). "Nowadays, there are two treatment modalities for advanced melanoma: molecular targeted therapy (inhibitors of BRAF and MEK kinases; BRAFi/MEKi) and immunotherapy with the usage of immune checkpoint inhibitors (anti-PD-1, -CTLA-4, and -LAG-3 antibodies)." (PMID 39340537, 2024). "Our phosphoproteomics and kinase prediction data clearly highlight different off-targets among clinically used BRAFi in endothelial cells, even though these molecules were all designed to target mutant BRAF in melanoma cells." (PMID 38839106, 2024). "In the short-term viability assay, CuET showed a dose-dependent killing effect on BRAF WT melanoma cell lines (SKMEL23, SKMEL113, WM1366) and BRAF WT PDSC lines (TÜMEL62-1, TÜMEL110, TÜMEL119, TÜMEL123-1, TÜMEL173, TÜMEL176)." (PMID 38263136, 2024). "Given the emergence of adverse events associated with immunotherapy, precision medicine represents a promising sphere of immunotherapy for personalized treatment of BRAF-mutant melanoma." (PMID 39336897, 2024). "Personalized therapy for BRAF-mutant melanoma represents a significant advancement over traditional treatment approaches by tailoring interventions based on individual genetic profiles." (PMID 39336897, 2024). "Preliminary experiments with cultured melanoma cells showed noticeable increases in trisomy 11 and 18 within cells which were BRAF-targeted therapy (vemurafenib) resistant." (PMID 38473384, 2024). "Regarding dabrafenib activity in BRAFV600E-mutant NSCLC, a favorable response was reported in a patient who had been enrolled in a trial for BRAF-mutant melanoma patients." (PMID 38731852, 2024). "The COMBI-AD trial has established the usage of dabrafenib/trametinib in the treatment of BRAF V600E mutant stage III melanoma." (PMID 39123418, 2024). "A randomized controlled study was conducted on patients with advanced melanoma and have progressed even after receiving ipilimumab and/or standard BRAF therapy." (PMID 38410760, 2024). "Recently, a phase III clinical trial was proposed aiming to evaluate the safety and efficacy of a combined BRAF+MEK inhibitor (encorafenib+binimetinib) in resected stage II BRAFV600-mutant melanoma patients." (PMID 39727691, 2024).
melanoma (continued). "Next, we investigated the effects of CuET as the major metabolite of DSF on trametinib treated BRAF WT melanoma cells." (PMID 38263136, 2024). "All the canine and equine melanoma cell lines detected BRAF exon 15 by means of Sanger sequencing or WES." (PMID 38397192, 2024). "Further studies and additional markers are necessary to identify those biomarkers that can predict PFS and other relevant patient outcomes for BRAF-mutant melanomas and response to treatment." (PMID 38473384, 2024). "However, other non-V600 BRAF variants may be found in advanced-stage melanoma." (PMID 38667446, 2024). "The phyto-sesquiterpene lactone DET and its derivative DETD-35 cause lipid ROS to accumulate, which leads to ferroptotic cell death in both BRAF-sensitive and BRAF-resistant V600E melanoma cells." (PMID 38336727, 2024). "We identified and collected tumor tissue blocks from twenty patients with BRAF-mutant melanomas: ten of those patients were treated first with targeted BRAF therapy, ten were treated first with either single-agent or dual immunotherapy." (PMID 38473384, 2024). "We observed a trend indicating enhanced neutrophil viability in coculture with melanoma cell lines under untreated, BRAF-/MEK-inhibitor-treated and cisplatin-treated conditions." (PMID 38730718, 2024). "Melanoma patients with previous targeted therapy (with BRAF and MEK inhibitors) experience a significantly longer time lapse between ICI initiation and VLL onset compared to non-pretreated patients (12.5 vs. 6.2 months)." (PMID 38392077, 2024). "For instance, KD-induced ketogenesis results in the accumulation of ketone bodies, enhanced BRAF signaling, and BRAF V600E melanoma progression." (PMID 38891772, 2024). "For instance, in mutant melanoma with BRAF inhibitor treatment, Grp78 binds the scaffold protein KSR2 to form a multiprotein complex, which acts independently of the UPR to activate ERK and promote the phosphorylation of ATF4." (PMID 38378757, 2024). "For example, scRNA-seq of BRAF-mutant melanoma cells treated with the BRAF inhibitor vemurafenib, alone or in combination with MEK inhibitor cobimetinib or trametinib, showed seven separate cell clusters representative of distinct transcriptional states." (PMID 38241976, 2024). "Different activating mutations have been identified in the melanoma subtypes of molecules that are part of this pathway, such as N-RAS, BRAF, MEK, and ERK; in fact, more than half of the reported melanoma mutations correspond to BRAF V600E." (PMID 39594467, 2024). "Based on data from the present study and others, BRAF-mutant GIST does not respond well to KIT TKIs but does respond well to combination BRAF and MEK inhibition, as is seen in other BRAF-driven cancers, such as melanoma." (PMID 38730662, 2024). "From an epidemiology standpoint, BRAF-mutant melanomas often occur in younger patients, frequently possessing a superficial diffusion or nodular morphology." (PMID 38539548, 2024). "The BRAF+ melanoma showed a substantially higher NES area percentage compared to dysplastic nevus (p = 0.0201) and melanoma in situ (p = 0.0160)." (PMID 39273022, 2024). "The effects were greater in the melanoma cell lines carrying the NRAS activating mutation, Q16K, except for invasion capacity, which was only seen in cell lines carrying the BRAF activating mutation, V600E." (PMID 39267923, 2024). "For example, dabrafenib competes with ATP for binding to the BRAF catalytic site and is thus indicated for BRAF V600+ melanoma." (PMID 38940147, 2024). "In summary, this study demonstrated that CTHRC1 was correlated with BRAF(V600E), prognosis, and clinicopathological features in colon cancer, thyroid cancer, and melanoma." (PMID 39052013, 2024). "The classification of the three experimental groups reflects the course of biopsy sampling under tumor-targeted therapy in patients with BRAF-mutant melanoma." (PMID 38631706, 2024).
melanoma (continued). "In melanoma, V600E is the most common BRAF mutation, whereas in NSCLC only half of the mutations affecting BRAF belong to this group." (PMID 38953007, 2024). "In this study melanoma cell lines resistant to treatment with BRAF and MEK inhibitors were obtained and characterized." (PMID 39175042, 2024). "RNA-based assays are instead preferable for detecting BRAF fusions which occur at low frequencies in melanoma (3%), glioma (2%) thyroid cancer (1%), pancreatic carcinoma (0.3%), NSCLC (0.2%), and colorectal cancer (0.2%)." (PMID 38539548, 2024). "All but one (88%) NF1-mutant melanomas that harbored chromothripsis involved interchromosomal SVs, compared with just 38% of BRAF-mutant melanomas with chromothripsis." (PMID 38758740, 2024). "Considering that the analysis of other markers besides BRAF is recommended in melanoma, the multi-gene approach using an NGS technique is preferable to sequential testing." (PMID 38667446, 2024). "In vivo analysis of a melanoma PDX model with acquired resistance to the BRAF inhibitor vemurafenib shows strong expression changes in a few genes but no activation of canonical pathways." (PMID 38255778, 2024). "This review explores the intricate interplay between genetic alterations, such as mutations in BRAF, NRAS, and KIT, and melanoma pathogenesis." (PMID 39200315, 2024). "Recent work has shown that AhR drives resistance to BRAF inhibitors in melanoma, and that AhR inhibition with resveratrol and flavinoids re-sensitize melanoma to BRAF inhibition." (PMID 38807762, 2024). "Mutations in BRAF, NRAS, NF1, and CKIT are sometimes referred to as “driver” mutations, as they rarely overlap each other in melanoma cells." (PMID 38339344, 2024). "Strikingly, VARS depletion significantly re-sensitized RES melanoma cells to BRAF inhibition (vemurafenib) in a dose-dependent manner." (PMID 38849541, 2024). "Previous research demonstrated a high prevalence of ALK expression in melanoma patients with wildtype BRAF or NRAS34,35." (PMID 39025927, 2024). "Atezolizumab, avelumab, and durvalumab are anti-PD-L1 agents that are mostly used in combination with targeted agents for the treatment of advanced BRAF-mutant melanoma." (PMID 39081713, 2024). "This is in contrast to BRAF wild-type melanomas, which usually develop after prolonged exposure to high doses of UV radiation, leading to solar elastosis." (PMID 38891988, 2024). "The NRAS-driven melanomas pose a particular challenge as they cannot be treated by the combinations of BRAF and MEK inhibitors." (PMID 39436655, 2024). "Compared to other observed groups, the strongest immunoreactivity was seen in the epithelium of BRAF+ melanoma and moderate in the BRAF− melanoma samples." (PMID 39273022, 2024). "A study on a mouse model of BRAF V600-mutant melanoma showed that the use of IT before TT maximized the antitumor efficacy." (PMID 38450188, 2024). "Our study confirms the co-occurrence of BRAF and NRAS mutations in melanoma and emphasizes the metastatic potential of a melanoma tumor that displays both of the mentioned mutations." (PMID 38396984, 2024). "Gene mutations of BRAF, especially BRAFV600E, and constitutively activated MAPK cascades drive multiple types of cancers, depriving differentiated features through melanoma genesis and intestine/colon carcinogenesis." (PMID 38750011, 2024). "The survival rates in relation to the high and low mRNA expressions of LOXL3, NES, and SNAI1 in both BRAF-positive (BRAF+) and BRAF-negative (BRAF−) melanoma were analyzed." (PMID 39273022, 2024). "It is now evident that, for asymptomatic BRAF-mutant melanoma patients, the combination of ipilimumab and nivolumab is the most effective treatment option." (PMID 39469641, 2024). "We also observed that miR-579-3p and MITF are positively correlated in BRAF-mutant melanoma cell lines." (PMID 38472212, 2024).